NAA25 (N-alpha-acetyltransferase 25, NatB auxiliary subunit)
Description:
Non-catalytic subunit of the NatB complex which catalyzes acetylation of the N-terminal methionine residues of peptides beginning with Met-Asp, Met-Glu, Met-Asn and Met-Gln. May play a role in normal cell-cycle progression.
Synonyms: C12orf30; MDM20; NAP1; FLJ13089
Tractability: Small molecule: a structure with a bound ligand is known. PROTAC: ubiquitination databases record sites on it; its protein half-life has been measured.
Gene: Protein-coding gene on chromosome 12 (112,026,689 to 112,109,434, reverse strand). Ensembl gene ENSG00000111300.
Subcellular location: Cytoplasm
Subcellular location (Human Protein Atlas): Cytosol; Golgi apparatus
Gene Ontology:
Molecular function: protein binding; acetyltransferase activator activity
Biological process: cytoskeleton organization
Cellular component: cytoplasm; cytosol; NatB complex
Genetic constraint (gnomAD): Loss-of-function variants: 19 observed, 81.78 expected, observed/expected ratio (o/e) 0.23, 90% interval 0.16 to 0.34. The upper end of that interval is the gene's LOEUF score, 0.34, which puts it in group 1 of 6, group 1 being the genes least tolerant of losing a copy. Missense variants: 566 observed, 876.51 expected, observed/expected ratio (o/e) 0.65, 90% interval 0.6 to 0.69. Synonymous variants: 273 observed, 319.11 expected, observed/expected ratio (o/e) 0.86, 90% interval 0.77 to 0.95.
Homologues: Orthologues: chimpanzee NAA25 (99% identical), macaque NAA25 (99% identical), guinea pig NAA25 (97% identical), pig NAA25 (97% identical), rabbit NAA25 (96% identical), mouse Naa25 (93% identical), dog NAA25 (92% identical), rat Naa25 (91% identical), tropical clawed frog naa25 (77% identical), zebrafish naa25 (71% identical), Drosophila melanogaster psidin (32% identical), Caenorhabditis elegans cra-1 (27% identical). Paralogues in human: NAA15 (17% identical), NAA16 (16% identical).
Diseases named in the same sentence as NAA25 in open-access papers:
NAA25 is named in the same sentence as 20 diseases in open-access papers, as found by Europe PMC text mining. Sharing a sentence is not in itself a finding about the gene and the disease. The quoted sentences say what the papers report.
type 1 diabetes (3 papers, 2010 to 2021). "NAA25 gene variants were reported as risk factors for type 1 diabetes, rheumatoid arthritis and acute arterial stroke." (PMID 35096568, 2021). "The same risk allele of SNP rs17696736 in the NAA25 gene has previously been associated with type 1 diabetes in a large genome-wide association study." (PMID 23041239, 2012). "NAA25 gene variants were reported to be associated with type 1 diabetes (T1D), rheumatoid arthritis, acute arterial stroke and dyslipidemia." (PMID 35096568, 2021).
B-cell lymphoma (1 paper, 2021). "And HSPH1 was highly expressed in different tumors, such as colorectal cancer, B-cell lymphoma, melanoma and esophageal squamous cell carcinoma, while NAA25 knockdown could upregulate IFIT2 and NDRG1 expression and downregulate HSPH1 expression." (PMID 35096568, 2021).
breast carcinoma (1 paper, 2021). "To explore the role of NAA25 gene in breast cancer, we analyzed its expression in different public databases." (PMID 35096568, 2021). "To better understand the function of NAA25 in breast cancer, we knocked down the expression of NAA25 in breast cancer cell lines, FACS was used to detect cell apoptosis and cell cycle and colony formation assay was used to detect cell proliferation." (PMID 35096568, 2021). "And NAA25 gene is highly expressed in breast cancer tissues relative to normal tissues, while high NAA25 expression is correlated with poor OS." (PMID 35096568, 2021). "According to TCGA and the Curtis, Finak breast and Richardson breast datasets, we found that NAA25 was greatly up regulated in breast cancer tissues in comparison with normal breast tissues." (PMID 35096568, 2021). "Based on the public database, such as TCGA and Curtis dataset, NAA25 gene is highly expressed in breast cancer tissues and this result has also been proved in our samples and cell lines through RT-qPCR and western blot analysis." (PMID 35096568, 2021). "In conclusion, in this study, we reported NAA25 as a candidate gene of rs11066150, which was highly expressed in breast cancer, and highly expressed NAA25 could reduce patient’s OS." (PMID 35096568, 2021). "Additionally, we explored the expression of NAA25 gene in breast cancer tissues and para-cancerous tissues." (PMID 35096568, 2021). "In addition, we tested NAA25 gene expression in breast cancer tissues, para-carcinoma tissues, breast cancer cell lines and normal breast epithelial cell lines." (PMID 35096568, 2021). "Together, our analyses reveal a previously unknown role of NAA25 in breast cancer, and highly expressed NAA25 might influence the progress of breast cancer." (PMID 35096568, 2021). "Taken together, our results revealed that NAA25 was highly expressed in breast cancer, and NAA25 knockdown might serve as a therapeutic target in breast cancer." (PMID 35096568, 2021). "This study is among the first attempts to clarify the function of NAA25 in breast cancer, and these results have elucidated the mechanism of NAA25 in breast cancer and suggests that NAA25 may serve as a potential therapeutic target of breast cancer." (PMID 35096568, 2021). "Furthermore, we specifically knocked down NAA25 gene expression in breast cancer cells and explored its influence on tumor cell proliferation, apoptosis and cell cycle." (PMID 35096568, 2021). "Hence, based on these results, we conclude that NAA25 is highly expressed in breast cancer and may lead to poor OS in patients by regulating tumor cell apoptosis and cell cycle." (PMID 35096568, 2021). "However, NAA25 gene was reported as a proto-oncogene in breast cancer for the first time, and more research is needed in the future to characterize the impact of rs11066150 A/G variant on breast cancer, and the relationship between lncHSAT164 and NAA25 gene also needs further study." (PMID 35096568, 2021). "However, the physiological function and mechanism of NAA25 in breast cancer remain unknown." (PMID 35096568, 2021). "We also monitored NAA25 expression in normal breast epithelial cell line MCF10A, and breast cancer cell lines MCF7 and T47D." (PMID 35096568, 2021).
tumor (3 papers, 2017 to 2025). "RNA-seq analysis was also applied to clarify the molecular profiling of NAA25-deficient cells, and NAA25 knockdown repressed tumor- and immune response-associated pathways." (PMID 35096568, 2021). "And NAA25 knockdown could increase apoptosis associated pathways, and reduce tumor associated pathways, like MYC, HIF1A, ERB2, MEK and TNF." (PMID 35096568, 2021). "RNA sequencing was then applied to analyze the molecular profiles of NAA25−deficient cells, and compared to the control group, NAA25 knockdown could activate apoptosis-related pathways, reduce the activation of tumor-associated signaling pathways and decrease immune response-associated pathways." (PMID 35096568, 2021). "To better define the role of hNatB in human HCC development we have now analyzed both NAA20 and NAA25 protein expression in paired tumor and non-tumor samples from 27 HCC patients (74% stage BCLC A and 26% stage B) treated with liver resection or transplantation." (PMID 28498797, 2017). "Indeed, we observed that in GBM, tumours with gain in the copy numbers of NAA25, the protein levels of NAA20, but not its transcript levels, were significantly increased." (PMID 38864963, 2025). "Interestingly, both subunits were up- or downregulated in 74% of analyzed tumor samples, indicating the expression of both subunits is co-regulated probably as a consequence of NAA20 degradation when it is not interacting with the accessory subunit NAA25." (PMID 28498797, 2017).
infection (2 papers, 2021). The state of being infected such as from the introduction of a foreign agent such as serum, vaccine, antigenic substance or organism. "GO term analysis was performed to NAA25-deficient cells, and the results showed that many genes were associated with infection and immunity." (PMID 35096568, 2021).
cancer (1 paper, 2021). A tumor composed of atypical neoplastic, often pleomorphic cells that invade other tissues. "RT-qPCR and western blot analyses were performed in four-pairs of tissues, and results revealed that NAA25 was highly expressed in cancer tissues." (PMID 35096568, 2021). "However, NAA25 gene has never been reported to be associated with cancers." (PMID 35096568, 2021).
NAA25 also shares sentences with these, for which no sentence is quoted: asthma (2 papers); gout (2); myocardial infarction (2); celiac disease (1); cervical cancer (1); colorectal cancer (1); coronary artery disease (1); esophageal squamous cell carcinoma (1); Hypertension (1); ischaemic stroke (1); melanoma (1); polyarthritis (1); rheumatoid arthritis (1); Stroke (1).